PRMT1 (protein arginine methyltransferase 1)
Diseases named in the same sentence as PRMT1 in open-access papers (continued):
Sharing a sentence is not in itself a finding about the gene and the disease.
breast carcinoma (continued). "PRMT1 is also involved in the interaction of many transcription factors and promoters, and the overexpression and abnormal splicing of PRMT1 directly affects the occurrence of tumors, including breast cancer, lung cancer, bladder cancer, leukemia, and colorectal cancer." (PMID 33853662, 2021). "Interestingly, our previous study also showed that PRMT1-mediated meR342-EZH2 is positively correlated with tumour size in breast cancer patients." (PMID 34775498, 2021). "We intended to explore whether PRMT1-mediated meR342-EZH2 is required for breast cancer cell proliferation in vivo by a subcutaneous xenograft mouse model assay." (PMID 34775498, 2021). "We also explored the predictive efficiency of PRMT1 in the survival of patients with breast cancer." (PMID 34440533, 2021). "On the one hand, we found that knockdown of PRMT1 decreased Cyclin E2, Cyclin B1 and CDK4 expression in MCF7 and MDA-MB-231 breast cancer cells; on the other hand, we also confirmed that ectopic expression of PRMT1 increased the expression of these mentioned proteins." (PMID 34775498, 2021). "Our data indicate that PRMT1 inhibitor GSK715 can repress breast cancer tumorigenesis, which may mainly through inhibiting PRMT1-mediated meR342-EZH2 methylation." (PMID 34775498, 2021). "To test this hypothesis, we first showed that overexpression of PRMT1 promoted cell proliferation in MCF7 breast cancer cells by CCK-8 assays, whereas knockdown of PRMT1 inhibited cell proliferation in MCF7 and MDA-MB-231 breast cancer cells." (PMID 34775498, 2021). "Recently, we have reported that PRMT1 is aberrantly expressed in breast cancer patients." (PMID 34440533, 2021). "PRMT1 was elevated in breast cancer cells, and PRMT1 was overexpressed in patients with TNBC." (PMID 34683150, 2021). "It is worth noting that ZEB1 may simultaneously contribute to the PRMT1-dependent inhibition of senescence in breast cancer cells." (PMID 34833023, 2021). "Finally, to evaluate the clinical significance of our findings, we conducted IHC assays in breast cancer TMA slides using anti-PRMT1, anti-meR342-EZH2 and anti-pT311-EZH2 antibodies." (PMID 34775498, 2021). "Protein arginine methyltransferase 1 (PRMT1) is able to promote breast cancer cell proliferation." (PMID 34775498, 2021). "Furthermore, PRMT1 inhibitors significantly impeded cell growth and promoted cellular senescence in breast cancer cells and primary tumor cells." (PMID 34440533, 2021). "PRMT1 can be detected in breast cancer, lung cancer, colon cancer, bladder cancer, and acute myeloid leukemia, but its expression may be disordered in different types of cancer." (PMID 32212935, 2020). "Since PRMT1, through BRCA1 methylation, controls the localization of BRCA1, we next examined whether PRMT1 protects breast cancer cells from IR-induced apoptosis." (PMID 32764667, 2020). "In addition, our recently study showed that PRMT1 specific inhibitor AMI-1 inhibits breast cancer cell invasion and migration through facilitate EZH2 degradation." (PMID 33308321, 2020). "Because BRCA1 needs to be translocated into the nucleus to perform its DNA-repairing functions, these results indicated that methylation of BRCA1 by PRMT1 may be necessary to activate BRCA1-dependent DNA repair in breast cancer cells that are subjected to IR." (PMID 32764667, 2020). "Thus, in breast carcinoma, PRMT1 methylates ZEB1 promoter, which then induces EMT and therefore implies ZEB1 as a negative prognostic parameter." (PMID 31655611, 2019). "Additionally, in breast cancer, patients with low expression of PRMT1 v1 display longer disease-free survival." (PMID 29383172, 2017). "We next examined if PRMT1 can affect the migration and invasion in breast cancer cells." (PMID 26813495, 2016).
breast carcinoma (continued). "Presumably, the mechanisms by which PRMT1 affects breast cancer progression may vary between PRMT1v1 and PRMT1v2, regarding the distinct characteristics of enzymatic activity, substrate specificity and subcellular localization." (PMID 26813495, 2016). "Based on the possibility that PRMT1 may be an important co-activator of PXR and PXR serves as a pivotal activator of P-gp, we supposed that PRMT1 inhibitor may decrease the expression of P-gp in resistant breast cancer cells." (PMID 26934120, 2016). "Furthermore, these authors demonstrated that the alternative splicing of PRMT1 pre-mRNA results in seven isoforms of the protein (PRMT1-v1 to v7), which differ in their N-terminal sequence, and are found to be dysregulated in breast cancer." (PMID 27556302, 2016). "Together, these data clearly demonstrate the critical role of PRMT1 in breast cancer metastasis." (PMID 26813495, 2016). "Our data revealed that, among the classic EMT-associated transcription factors (Twist, Snail, Slug and ZEB1) we tested, only the expression of ZEB1 was found to be regulated by PRMT1, and the PRMT1-mediated activation of ZEB1 was crucial for initiation of EMT process in breast cancer cells." (PMID 26813495, 2016). "Finally, we used dual luciferase reporter gene systems and nude mice bearing resistant breast cancer cells to identify the anti-tumor effect of PRMT1 inhibitors in vitro and in vivo." (PMID 26934120, 2016). "Together, these results implicate that PRMT1 is a novel regulator of EMT in breast cancer cells." (PMID 26813495, 2016). "To understand the mechanism by which PRMT1 participates in breast cancer EMT and metastasis, we tested whether PRMT1 can activate the expression of the crucial EMT inducers." (PMID 26813495, 2016). "Methylation of ERα by PRMT1 associated with oestrogen non-genomic signaling activation is increased in aggressive breast cancer." (PMID 25951181, 2015). "Recent studies have shown that PRMT1 acts as an epigenetic transcription regulator by activating gene transcription, thereby regulating the occurrence and development of a variety of tumors, including breast cancer, hepatocellular carcinoma, and colorectal cancer." (PMID 40858547, 2025). "Notably, the inhibitor of PRMT1 (iPRMT1) was able to inhibit breast cancer cell growth, and the iPRMT1 was even more effective when combined with inhibitors targeting SRSF1 phosphorylation (SPHINX31 and SRPIN340), suggesting the potential value of combination therapy." (PMID 40129567, 2025). "In addition, PRMT1 expression was higher in ALDH+ breast cancer cells." (PMID 40927753, 2025). "For instance, PRMT1 could promote lung cancer growth and breast cancer metastasis." (PMID 37558663, 2023). "Whether PRMT1 regulates the Wnt pathway in breast cancer cells is still unknown." (PMID 35053470, 2022). "It is possible that PRMT1 circRNA transcripts are preferentially produced in distinct subtypes of breast cancer, while aberrant alternative splicing of PRMT1 circRNAs may act as a driver for breast cancer tumorigenesis through the deregulation of important molecular functions." (PMID 35885916, 2022). "Besides, multivariate analysis indicated that the high PRMT1 expression in breast cancer tissues could be an independently prognostic marker of poor prognosis." (PMID 34440533, 2021). "In addition, we also revealed that the PRMT1 specific inhibitor Fur blocks cell growth and induces apoptosis and senescence in breast cancer cell lines and primary cells, demonstrating the antitumor effects of Fur on breast cancer cells." (PMID 34440533, 2021). "However, the detailed mechanisms of PRMT1-mediated breast cancer cell proliferation are largely unknown." (PMID 34775498, 2021).
breast carcinoma (continued). "Therefore, we wondered whether PRMT1-mediated EZH2 methylation is able to promote breast cancer cell proliferation and tumorigenesis." (PMID 34775498, 2021). "Since PRMT1-dependent methylation of BRCA1 contributes to the epigenetic defense of breast cancer cells to IR (and probably to other DNA damage agents), these could explain, at least in part, why PRMT1 has been identified as a marker of unfavorable prognosis for breast cancer patients." (PMID 32764667, 2020). "Thus, we have identified a novel role and regulatory mechanism of PRMT1 in breast cancer cell proliferation and metastasis, which may provide clues for the development of new epigenetic intervention targeting PRMT1 for advanced breast cancers." (PMID 26813495, 2016). "Moreover, PRMT1 promoted the migratory and invasive behaviors in breast cancer cells." (PMID 26813495, 2016). "We then explored whether PRMT1 can trigger EMT in breast cancer cells." (PMID 26813495, 2016). "Ongoing trials are evaluating additional PRMT inhibitors, including GSK3368715 (targeting PRMT1) and CMP5 (targeting PRMT5), in patients with advanced malignancies, including breast cancer." (PMID 40791817, 2025). "We aim to clarify the complex role of PRMT1 in TNBC, an aggressive and treatment-resistant breast cancer subtype, by exploring its impact on cell proliferation, migration, invasion, chemoresistance, and lung metastasis." (PMID 40927753, 2025). "Again, protein levels of PRMT1/PRMT5 were generally higher in ES cells compared to MCF7 and SUM159 breast cancer lines." (PMID 40823091, 2025). "Meanwhile, PRMT1 can facilitate the asymmetric methylation modification of EZH2, enhancing its protein stability and promoting the EMT process of breast cancer cells, which ultimately leads to breast cancer metastasis." (PMID 39890802, 2025). "Another characteristic of cancer cells that PRMT1-mediated H4R3 methylation regulates is the epithelial–mesenchymal transition (EMT) and senescence in breast cancer." (PMID 40001488, 2025). "A study demonstrated that PRMT1 was able to induce the EMT process and enhance the capabilities of migration and invasion in breast cancer cells." (PMID 41154773, 2025). "From the GEO DataSets GSE42568, we found that PRMT1, PRMT2, and CARM1 were highly expressed in breast cancer cells." (PMID 38476024, 2024). "EZH2 R342 can be methylated by PRMT1, which increases epithelial–mesenchymal transition (EMT) in breast cancer cells and predicts poor prognosis in breast cancer patients." (PMID 37143582, 2023). "Searching for new therapeutic targets, we found that PRMT1 is highly expressed in TNBC tumor samples and is essential for breast cancer cell survival." (PMID 35053470, 2022). "Several studies have confirmed that PRMT1, PRMT2, PRMT3, and PRMT7 are overexpressed in breast cancer." (PMID 35216622, 2022). "Asymmetrically dimethylated EZH2 by PRMT1 impedes the phosphorylation and ubiquitylation of EZH2 to regulate breast cancer metastasis." (PMID 35921899, 2022). "Our recent studies demonstrated that PRMT1-mediated EZH2-R342 ADMAs (meR342-EZH2) strengthen protein stability and enhance breast cancer metastasis." (PMID 34775498, 2021). "Our group highlighted that a PRMT1-dependent hypermethylation of ERα at R260, induced in response to estrogen or IGF-1, is observed in different subtypes of breast cancers and regulates cell proliferation and survival." (PMID 34833023, 2021). "In this study, we observed that the PRMT1 inhibitors AMI-1 and GSK715 significantly inhibited MDA-MB-231 breast cancer cell proliferation." (PMID 34775498, 2021). "We also discovered that meR342-EZH2 is positively correlated with PRMT1 expression in breast cancer tissues, whereas meR342-EZH2 is negatively correlated with pT311-EZH2 expression in breast cancer tissues." (PMID 34775498, 2021).
breast carcinoma (continued). "Elevated expression of PRMT1 and CYP11A1 was observed in highly metastatic human breast cancer cell lines and knockdown of these genes through RNA interference suppressed the motility and invasion of MDA-MB-231 cells without affecting their viability." (PMID 34919051, 2021). "Overall, these clinical data indicated that PRMT1 and meR342-EZH2 expression has a positive correlation in breast cancer patients." (PMID 34775498, 2021). "The presence of active PRMT1 favored the formation of BRCA1 foci after IR, whereas the absence of this methylase induced the accumulation of 53BP1 foci in breast cancer cells." (PMID 32764667, 2020). "We conclude that by modulating the cellular localization of BRCA1, PRMT1 is an important regulator of the oncogenic functions of BRCA1, contributing to the epigenetic defense of breast cancer cells against ionizing radiation." (PMID 32764667, 2020). "To summarize, we describe in this report a novel function of PRMT1 in modulating both EMT and cell growth in breast cancer cells." (PMID 26813495, 2016). "Specifically, PRMT1 is an important inducer for EMT, and is essential for the acquisition of stem cell properties and maintenance of proliferation in breast cancer cells." (PMID 26813495, 2016). "In this study, we demonstrated that PRMT1 was able to induce the EMT process and to enhance the capabilities of migration and invasion in breast cancer cells." (PMID 26813495, 2016). "Upon complete abrogation of endogenous PRMT1, and with the use of a PRMT1-specific inhibitor, cell viability was attenuated in triple-negative breast cancer cell lines (TNBC1 and TNBC2), one of the most aggressive forms of breast cancer." (PMID 40001488, 2025). "Furthermore, our research group has previously discovered that PRMT1 mediates asymmetric methylation modification on the R342 site of EZH2, leading to enhanced stability of the EZH2 protein and promotion of breast cancer metastasis." (PMID 39890802, 2025). "The impact of circRNAs derived from the protein arginine methyltransferase 1 (PRMT1) gene has not been clarified yet, even though the effect of PRMT1-mediated methylation on breast cancer cell characteristics has been well established." (PMID 37692475, 2024). "PRMT1 expression was negatively correlated with the infiltration of CD8+ T cells and macrophages and was reversely correlated with the effector T cell signature in breast cancer." (PMID 39201539, 2024). "Additionally, the data in GSE65194 showed that PRMT1, PRMT3, CARM1, PRMT5, and PRMT6 were highly expressed in basal-like breast cancer." (PMID 38476024, 2024). "Nevertheless, some non-basal breast cancer cell lines are also dependent on PRMT1, indicating the potential of PRMT1 as a therapeutic target in these breast cancer types." (PMID 35578032, 2022). "Moreover, a mechanism that activates ZEB1 is the asymmetric dimethylation of H4R3 by PRMT1 at the ZEB1 promoter, which promotes migration, invasion, and the acquisition of stem cell properties of breast cancer cells." (PMID 35885916, 2022). "PRMT1-v6 expression has so far not been detected in any normal human tissues but was detected in certain breast cancer cell lines." (PMID 34833023, 2021). "Interestingly, in breast cancer cells MCF7, a high density of PRMT1 was found inside the cell nucleus, while osteosarcoma U2OS cells were characterized by PRMT1 localization in the cytoplasm." (PMID 34357041, 2021). "For example, methylation of C/EBPα at R35, R156 and R165 by PRMT1 prevents its interaction with the corepressor HDAC3, thus promoting the expression of cell-cycle genes such as cyclin D1 and the subsequent growth of breast cancer cells." (PMID 34833023, 2021).
breast carcinoma (continued). "The decrease of the poly-ubiquitylated forms of Bcl-2 in cells depleted of BRCA1, independently of PRMT1 expression, also confirmed that cytosolic BRCA1 might control the stability of Bcl-2 in breast cancer cells." (PMID 32764667, 2020). "In addition, our newest study found that PRMT1-mediated R342-EZH2 asymmetric di-methylation (ADMA) strengthens EZH2 stability and promotes breast cancer metastasis." (PMID 33308321, 2020). "Interestingly, PRMT1 knockdown was also correlated with decreased EGFR activity and suppressed proliferation of in MDA-MB-468 breast cancer cells that are derived from an African American breast cancer patient." (PMID 32873298, 2020). "Altogether, these results indicated that PRMT1 is an important component of the epigenetic defense of breast cancer cells against IR and that cytosolic BRCA1 is required for IR-induced apoptosis in breast cancer cells." (PMID 32764667, 2020). "The function of PRMT1 in modulating EMT was suggested through the regulation of Zinc Finger E-Box Binding Homeobox 1 (ZEB1) in breast carcinoma and Twist Family BHLH Transcription Factor 1 (TWIST1) in non-small lung carcinoma." (PMID 31655611, 2019). "Although the involvement of protein arginine methyltransferase 1 (PRMT1) in tumorigenesis has been reported, its roles in breast cancer progression and metastasis has not been elucidated." (PMID 26813495, 2016). "HeLa cells were chosen as they display high levels of PRMT1 expression in contrast to other breast cancer cell lines (data not shown)." (PMID 20614009, 2010). "Similarly, PRMT1, PRMT2, PRMT3, PRMT4, and PRMT7 are highly expressed in breast cancer tissues." (PMID 37143582, 2023). "In fact, in PRMT1-silenced breast cancer cells, BRCA1 did not accumulate in the nucleus after IR." (PMID 32764667, 2020). "Finally, those PRMT1 inhibitors were observed to significantly decrease MDR1 promoter activity in vitro and enhance the antitumor effect of adriamycin in nude mice that bearing resistant breast cancer xenografts." (PMID 26934120, 2016). "MCF7 cells depleted of PRMT1 or BRCA1 showed a significant decrease in Bcl-2 protein, but experiments in the presence of MG132, a proteasome inhibitor, and analysis of Bcl-2-mRNA indicated that BRCA1 and PRMT1 might differentially regulate Bcl-2 protein levels in breast cancer cells." (PMID 32764667, 2020). "Moreover, PRMT1 inhibitors could concomitantly target nongenomic ERα and IGF-1 signaling, two pathways largely implicated in breast cancer development." (PMID 30692633, 2019). "In addition, PRMT1 may be involved in breast cancer development via the methylation of non-histone substrates, estrogen-receptors (ER)." (PMID 23977297, 2013). "We also verified the PRMT1-meR342-EZH2-positive expression correlation and meR342-EZH2-pT311-EZH2 -negative expression correlation in breast cancer tissue samples." (PMID 34775498, 2021). "As we previously showed that PR is not methylated in the absence of progesterone, we proposed that PRMT1 could be a novel actor of PR downregulation prior to hormonal stimulation, acting with BRCA1 in the recycling of unliganded PRs in breast cancer cells." (PMID 36076907, 2022). "Finally, our data provide a rationale for the use of PRMT1 inhibitors to concomitantly target IGF-1 and estrogen nongenomic pathways in ERα-positive breast cancer therapies." (PMID 30692633, 2019).